MEIOB (meiosis specific with OB-fold)
Description:
Single-stranded DNA-binding protein required for homologous recombination in meiosis I. Required for double strand breaks (DSBs) repair and crossover formation and promotion of faithful and complete synapsis. Not required for the initial loading of recombinases but required to maintain a proper number of RAD51 and DMC1 foci after the zygotene stage. May act by ensuring the stabilization of recombinases, which is required for successful homology search and meiotic recombination. Displays Single-stranded DNA 3'-5' exonuclease activity in vitro.
Synonyms: C16orf73; MGC35212; POF23; SPGF22; gs129
Tractability: No criterion of Open Targets' tractability assessment is met for any kind of drug.
Gene: Protein-coding gene on chromosome 16 (1,833,986 to 1,884,294, reverse strand). Ensembl gene ENSG00000162039.
Subcellular location: Cytoplasm; Nucleus; Chromosome
Gene Ontology:
Molecular function: protein binding; single-stranded DNA binding; chromatin binding; single-stranded DNA 3'-5' DNA exonuclease activity
Biological process: double-strand break repair via homologous recombination; female meiosis I; fertilization; homologous chromosome pairing at meiosis; male meiotic nuclear division; reciprocal meiotic recombination; resolution of meiotic recombination intermediates; male meiosis I
Cellular component: cytoplasm; nucleus; chromosome
Genetic constraint (gnomAD): Loss-of-function variants: 14 observed, 16.6 expected, observed/expected ratio (o/e) 0.84, 90% interval 0.56 to 1.32. The upper end of that interval is the gene's LOEUF score, 1.32, which puts it in group 5 of 6, group 1 being the genes least tolerant of losing a copy. Missense variants: 238 observed, 257.73 expected, observed/expected ratio (o/e) 0.92, 90% interval 0.83 to 1.03. Synonymous variants: 96 observed, 90.54 expected, observed/expected ratio (o/e) 1.06, 90% interval 0.9 to 1.26.
Homologues: Orthologues: chimpanzee MEIOB (99% identical), macaque MEIOB (95% identical), guinea pig MEIOB (86% identical), dog MEIOB (86% identical), mouse Meiob (85% identical), pig MEIOB (85% identical), rat Meiob (83% identical), rabbit MEIOB (82% identical), tropical clawed frog meiob (63% identical), zebrafish meiob (49% identical), Drosophila melanogaster hdm (25% identical).
Diseases named in the same sentence as MEIOB in open-access papers:
MEIOB is named in the same sentence as 15 diseases in open-access papers, as found by Europe PMC text mining. Sharing a sentence is not in itself a finding about the gene and the disease. The quoted sentences say what the papers report.
Azoospermia (3 papers, 2022 to 2024). Absence of any measurable level of sperm,whereby spermatozoa cannot be observed even after centrifugation of the semen pellet. "Pathogenic variants in MEIOB were shown to cause POI and non-obstructive azoospermia (NOA) in a consanguineous family." (PMID 38672141, 2024). "MEIOB has been found to be associated with premature ovarian insufficiency (POI) and non-obstructive azoospermia (NOA), but its variants have not been reported in Chinese patients." (PMID 35991565, 2022).
Infertility (3 papers, 2021 to 2024). "This MEIOB variant is expected to provoke meiotic defects and a depleted follicular stock, consistent with the phenotype of the Meiob −/− mouse that displays infertility in both sexes due to meiotic arrest." (PMID 33806855, 2021). "However, variants of MEIOB associated with human infertility are rare, with only 10 cases reported so far, and none of the variants have been reported in the Chinese patients with POI or NOA." (PMID 35991565, 2022). "Previous studies have reported that mutations in MEIOB may cause infertility in males and females." (PMID 35991565, 2022). "MEIOB knockout mice (Meiob−/−) exhibit infertility in both sexes, resulting from meiotic arrest at a zygotene/pachytene-like stage." (PMID 35991565, 2022). "The currently reported phenotypes and genotypes of MEIOB gene in infertility patients." (PMID 35991565, 2022).
lung adenocarcinoma (2 papers, 2016 to 2024). A carcinoma that arises from the lung and is characterized by the presence of malignant glandular epithelial cells. "In lung adenocarcinoma, MEIOB overexpression increases cell viability, proliferation, and the proportion of cells in the G2 phase." (PMID 38596293, 2024). "We show that the meiosis-related EECTG (MEIOB) and its nearby CT-ncRNA have a role in tumorigenesis in lung adenocarcinoma." (PMID 26813108, 2016). "MEIOB expression is positively correlated with the copy number aberrations in lung adenocarcinoma, bladder urothelial carcinoma, thyroid carcinoma, and uterine corpus endometrial carcinoma and its expression positively correlates with poor survival in triple negative breast cancer." (PMID 38596293, 2024). "After subsequent validation, we demonstrated that a meiosis-related EECTG (MEIOB) and its companion testis-specific ncRNA (TS-ncRNA; LINC00254) play crucial roles in carcinogenesis in lung adenocarcinoma (LUAD)." (PMID 26813108, 2016).
lung carcinoma (2 papers, 2022). "Overexpression of MEIOB in lung cancer cells increases cell viability and malignant phenotypes; whereas the deletion of MEIOB inhibits lung cancer cell colony formation, growth, invasion and migration." (PMID 35574342, 2022).
male infertility (2 papers, 2020 to 2025). The inability of the male to effect fertilization of an ovum after a specified period of unprotected intercourse. "Mutations at multiple sites in MEIOB are associated with male infertility." (PMID 40867525, 2025).
Premature ovarian insufficiency (2 papers, 2022 to 2025). Amenorrhea due to loss of ovarian function before the age of 40. "In this context, a correlation between MEIOB loss-of-function and premature ovarian insufficiency has been demonstrated." (PMID 39676663, 2025).
triple-negative breast carcinoma (2 papers, 2021 to 2022). An invasive breast carcinoma which is negative for expression of estrogen receptor (ER), progesterone receptor (PR), and human epidermal growth factor receptor 2 (HER2). "Overexpression of the MEIOB gene has been observed in triple-negative breast cancer (TNBC) cells, which is confirmed that ectopic expression of MEIOB is oncogenic and promotes cancer cell proliferation." (PMID 35991565, 2022). "In this study, we aimed to investigate the effects and mechanisms of MEIOB in the carcinogenesis of triple-negative breast cancers (TNBCs)." (PMID 33628586, 2021).
breast carcinoma (1 paper, 2021). "To exclude the influence of BRCA1/2, we found that MEIOB expression was mutually exclusive with mutations in BRCA1/2 in both breast cancers and TNBCs (P < 0.01)." (PMID 33628586, 2021). "The results of IHC analysis of breast cancer tissues confirmed the upregulation of MEIOB protein levels in TNBCs when compared with both luminal cancers and adjacent tissues (NTNBC = 52, NLuminal = 32, NAdjacent = 32)." (PMID 33628586, 2021). "To better understand the role of MEIOB in breast cancer, we then knocked down MEIOB by using siRNA in MDA-MB-231 cells and found that depletion of MEIOB in MDA-MB-231 cells led to a significant decrease in both cell proliferation and migration." (PMID 33628586, 2021). "Taken together, our study showed that the CT gene, MEIOB, promoted breast cancer cell viability and mediated HRD by activating the PARP1-dependent DNA damage response." (PMID 33628586, 2021). "Notably, we found that the score of signature 3 was correlated with MEIOB and was significantly higher in patients with high MEIOB expression in TCGA breast cancer datasets." (PMID 33628586, 2021). "Furthermore, the pHR-GFP reporter vector was used to assess the effect of MEIOB expression on DNA damage repair by homologous recombination in SUM1315MO2 breast cancer cells." (PMID 33628586, 2021). "To validate the hypothesis that MEIOB affected the viability of breast cancer cells, we first conducted RT-PCR and Western blot to examine the mRNA and protein expressions of MEIOB in various types of breast cancer cell lines." (PMID 33628586, 2021).
breast tumors (1 paper, 2021). "We confirmed MEIOB as a CT gene whose expression was restricted to the testes and breast tumors, especially TNBCs." (PMID 33628586, 2021).
melanoma (1 paper, 2024). A malignant, usually aggressive tumor composed of atypical, neoplastic melanocytes. "The TWAS detected 27 genes associated with melanoma with p-values less than 0.05 (the top three genes are LOC389458 (RBAK), C16orf73 (MEIOB), and EIF3CL)." (PMID 39061157, 2024).
cancer (6 papers, 2016 to 2023). A tumor composed of atypical neoplastic, often pleomorphic cells that invade other tissues. "The newly defined cancer-testis (CT) gene, MEIOB, was previously found to play key roles in DNA double-strand break (DSB) repair." (PMID 33628586, 2021). "To prove that MEIOB plays a critical role during the development of cancer, we designed a series of in vitro experiments." (PMID 26813108, 2016). "However, we recommend that patients who have mutations in the MEIOB or other DSB repair-related genes, should undergo regular check-up and screening for early detection and timely intervention of cancer." (PMID 35991565, 2022). "Importantly, there was a positive correlation between MEIOB and the genome-wide burden of focal copy number aberrations among samples from 10 cancer types with activation of MEIOB and SPATA22 expression." (PMID 27275820, 2016). "In addition, the expression of MEIOB was positively correlated with the genome-wide burden of focal copy number aberrations (CNAs) among samples from 10 cancer types with MEIOB and SPATA22 activation (Spearman's rank correlation coefficient=0.12, P=8.30 × 10−14)." (PMID 26813108, 2016). "Examples include the HORMAD1/2, MND1, MEIOB and SYCP3 genes, which directly influence the HR activity of cancer cells." (PMID 35251135, 2022). "The co-factor for MEIOB (SPATA22) in meiosis recombination, which was co-expressed with MEIOB in testis, displayed mutually exclusive expression pattern in samples with LUAD and other cancer types." (PMID 26813108, 2016). "Meiosis Specific with OB Domains (MEIOB) was recently shown to be a DNA binding exonuclease essential for meiotic recombination in synergy with SPATA22, and this protein has been detected in different types of cancer cells." (PMID 27275820, 2016).
tumor (2 papers, 2016 to 2021). "MEIOB is a newly identified CT gene that is expressed both in the testes and in tumor tissues from TNBC patients." (PMID 33628586, 2021). "Thus, we concluded that MEIOB may promote tumor proliferation in TNBCs." (PMID 33628586, 2021). "We also observed similar MEIOB and SPATA22 activation in other tumour types." (PMID 26813108, 2016).
MEIOB also shares sentences with these, for which no sentence is quoted: cancer testis (1 paper); oligospermia (1); spermatogenic failure (1).